MMP9 (matrix metallopeptidase 9)
Diseases named in the same sentence as MMP9 in open-access papers (continued):
Sharing a sentence is not in itself a finding about the gene and the disease.
tumor (continued). "The MMP9 inhibitors are expected to be used for regulating inflammatory response and tumor advancement (Kalhori and Törnquist, 2015; Muthukuru and Cutler, 2015)." (PMID 40356970, 2025). "The combined management of RES with temozolomide caused cell cycle arrest, decreases of MMP9, and anti‐apoptosis protein Bcl‐2 in the human GB cell line (SHG44), and reduced the volume of the tumor in an orthotopic xenograft model of GB." (PMID 40400263, 2025). "Knockdown of AHNAK2 has been shown to impede tumor progression through inhibition of the NF-κB/MMP-9 signaling pathway." (PMID 40308776, 2025). "Factors released from neutrophils, such as arginase-1, MMP-9 (matrix metalloproteinase-9), or VEGFs, can promote angiogenesis and tumor development." (PMID 40358184, 2025). "NE and MMP9 released from NETs cleave adhesion proteins and activate integrin α3β1-dependent signaling, thereby reigniting dormant tumor cell proliferation." (PMID 40564191, 2025). "Our results demonstrate significantly higher MMP-9 activity in tumor tissue compared to adjacent tissue and healthy control tissue." (PMID 40729026, 2025). "The association between tumor AOPPs and NF-κB marginally lost its significance, but tumor AOPPs were significantly correlated with tumor MMP-9 activity." (PMID 40729026, 2025). "Our findings revealed a downregulation of LCN-2 and an upregulation of MMP-9 gene expression in tumor tissues compared to healthy counterparts." (PMID 40214460, 2025). "Among them, MMP-9, also known as gelatinase B or 92-kDa type IV collagenase, plays a pivotal role in tumor invasion and angiogenesis by mediating the degradation of vascular structures that support tumor growth." (PMID 40729026, 2025). "By regulating VEGF to promote angiogenesis within tumors, MMP-9 plays a critical role in tumor invasion and metastasis." (PMID 40458729, 2025). "Prior studies have also shown that IR, especially high-LET radiation induces a robust SASP characterized by increased secretion of TGFβ1, MMP9, IL-6, and IGFBPs, promoting chronic inflammation and tumor progression." (PMID 41516087, 2025). "M2 macrophages promote cancer cell growth, invasion, and metastasis by secreting factors like TGF-β and MMP-9, which enhance the tumor’s invasive potential." (PMID 40330466, 2025). "Single‐cell transcriptomic studies reveal that tumor‐associated neutrophils (TANs) infiltrating the PMN enhance LEC proliferation and lymphatic sprouting via ERK/JNK‐mediated secretion of MMP9 and VEGFA." (PMID 40470380, 2025). "In CCA, chronic inflammation and oxidative damage promote a tumor microenvironment where MMP9 is activated, enhancing epithelial–mesenchymal transition (EMT) and immune evasion." (PMID 41300430, 2025). "Numerous studies utilize MMP-9-targeted vectors as nanoprobes for tumor cell detection, diagnosis, and assessment of invasiveness." (PMID 40284474, 2025). "The progression of PCa is likely influenced by the interplay of these targets where FGFR1 drives tumor growth and metastasis, MMP-9 facilitates invasion, and PDGFRB promotes tumor growth and angiogenesis." (PMID 40429793, 2025). "These cells release cytotoxic substances, such as reactive oxygen species (ROS), nitric oxide (NO), and matrix metalloproteinase-9 (MMP-9), which directly kill tumor cells and enhance the radiation response." (PMID 41450947, 2025). "PEVs have been shown to enhance tumor cell invasion by stimulating MMP-2 synthesis and secretion, as well as by promoting the transcription of MMP-9, VEGF, IL-8, and HGF mRNAs, factors closely associated with lung cancer metastasis." (PMID 41383620, 2025). "Neutrophils further promote tumor growth and angiogenesis through the secretion of factors like MMP-9 and neutrophil elastase." (PMID 40352665, 2025). "Specifically, neutrophils release ROS and MMP-9 to disrupt the tumor extracellular matrix (ECM) and induce DNA damage; macrophages produce NO via inducible nitric oxide synthase (iNOS) to directly kill tumor cells." (PMID 41450947, 2025).
tumor (continued). "Elevated levels of MMPs, especially MMP-9, are considered an important factor in hepatocarcinogenesis and a promoter of tumor invasion and angiogenesis." (PMID 40740310, 2025). "MMP9 functions as an important mediator of processes essential for tumour development, including ECM remodelling, EMT, cell migration, angiogenesis and immune response modulation." (PMID 40830065, 2025). "Low-molecular-weight heparin-tocopheryl succinate (TOS) nanoparticles inhibited G-MDSC-produced MMP-9 and prevented early lung recruitment of tumor-induced G-MDSCs, impeding tumor invasion and colonization." (PMID 40284474, 2025). "MMP-9 plays a crucial role in tumor and vascular disease development and progression, offering significant diagnostic and therapeutic potential." (PMID 40284474, 2025). "Studies have shown that high levels of MMP-2 and MMP-9 correlate with poor patient prognoses, greater tumor invasiveness, and shorter survival times." (PMID 40265458, 2025). "While previous research has established MMP9’s involvement in various mechanisms of tumour invasion and metastasis, it is essential to recognize that these capabilities do not necessarily encompass or equate to anoikis resistance." (PMID 40830065, 2025). "Under hypoxic conditions, HIF-1α directly induces MMP9 transcription, facilitating basement membrane degradation and tumour cell extravasation." (PMID 40806577, 2025). "Fucoidan, for example, has been reported to downregulate MMP-2 and MMP-9, enzymes critical for extracellular matrix degradation and tumor invasion." (PMID 41311846, 2025). "Gold nanorods (Au NRs) can inhibit tumor invasion and metastasis by altering the structure of matrix metalloproteinase-9 (MMP-9), a key enzyme in cancer progression." (PMID 40649877, 2025). "This role for MMPs in tumor pathophysiology also makes them a potential therapeutic target, and high levels of MMP2, MMP9, MMP15, MMP16 have been shown to be expressed in GBM tumor cells and associated with poor prognoses." (PMID 41400763, 2025). "The pharmacokinetics of these nanocontrast agents allows for the observation of MMP-9 expression variations among tumors and the assessment of biological behaviors, including tumor invasiveness." (PMID 40284474, 2025). "Tumor samples exhibited significantly elevated expression of multiple immune- and inflammation-related genes, including MMP9, TNF, and members of the S100A family." (PMID 40678068, 2025). "MAPK7 and therefore MMP9 silencing significantly minimised M2 like TAM infiltration at the tumour site, M1 to M2 polarisation and lung colonisation." (PMID 40442778, 2025). "Another study has shown that high doses of melittin attenuated the mRNA and protein expression of MMP-2 and MMP-9 in osteosarcoma 143 B cells, leading to reduced tumor metastasis." (PMID 40141020, 2025). "Given their established roles in pre-metastatic remodeling, PMN lung tissue samples from days 11 and 14 post-tumor induction were analyzed for MMP9, fibronectin, and the chemoattractant cytokines S100A8 and S100A9 using ELISA assays." (PMID 40649918, 2025). "In univariate analysis HA, HAS-2, HYAL-1, Slug, MMP-9, and N-Cadh staining in tumor tissues significantly correlated with metastasis (p ≤ 0.002 in each case)." (PMID 40149256, 2025). "MMP9 is an important matrix metalloproteinase, which plays a key role in the process of tumor invasion and metastasis, inflammation response and so on." (PMID 40129948, 2025). "Tumor cells disrupt the integrity of the BBB by secreting protein hydrolases such as MMP‐9 but also limit the effective delivery of most therapeutic agents." (PMID 41245887, 2025).
tumor (continued). "For recurrent GBM, acyl sphingosine amidohydrolase 1 (ASAH1, an enzyme that regulates ceramide metabolism) increases alongside MMP-9 within NETs, which promotes the formation of NETs and their pro-tumor function." (PMID 40868150, 2025). "The positive correlation between the expression of MMP9 and the abundance of gut microbiome in the current study indicates the significant role of gut microbiome in inducing tumor progression and invasion." (PMID 41326479, 2025). "In line with the reduced neutrophil numbers in tumor samples, we observed reduced MMP9 expression in tumor tissue of Gpr4−/− animals compared to WT." (PMID 40397803, 2025). "The activated NF-κB complex co-activates histone acetyltransferases CBP/p300 and PCAF, which acetylate histones and further promote MMP-9 transcription, thereby enhancing basement membrane degradation and tumor invasion." (PMID 41036604, 2025). "↑ Bax pro‐apoptotic protein → ↓ Bcl‐2, NF‐κB, and MMP‐9 → apoptosis induction and tumor growth inhibition." (PMID 40761486, 2025). "Specifically, LATS1 exerts tumor-suppressive functions by increasing p27 levels, decreasing cyclin E and matrix metalloproteinase-9 (MMP-9), and promoting YAP phosphorylation." (PMID 41256331, 2025). "T3 stadium also has a high activity of MMP-9, since the tumor is making a distant metastasis and there is a need for ECM degradation." (PMID 40729026, 2025). "Namely, MMP9 is over-expressed by endothelial cells and MAC1+/VEGFR1+ myeloid cells in PMN, and its expression has not only been associated with tumor cell invasion but also with the recruitment of BMDC to the niche." (PMID 41383620, 2025). "Subsequent western blotting confirmed reduced expression of POSTN, Snail, and MMP9 in POSTN-knockdown xenograft tumor tissues, suggesting the inhibition of SCLC metastatic abilities through the downregulation of EMT-related genes." (PMID 39762921, 2025). "Destruction of the ECM is a necessary step during tumor invasion and metastasis, and studies have shown that MMP-9 is overexpressed in PDAC." (PMID 41471188, 2025). "These polyphenols (e.g., caffeoylquinic acids) can also downregulate MMP-2 and MMP-9, limiting tumor cell proliferation and invasion." (PMID 41517157, 2025). "Matrix metalloproteinases (MMPs), particularly MMP‐9 and gelatinase B, facilitate tumor invasion and metastasis by degrading the ECM." (PMID 41049266, 2025). "Correspondingly, tumor growth curves showed that MMP9 inhibition abrogated the antitumor efficacy of tdRT→αPD-1." (PMID 40675962, 2025). "For example, the infiltration of CD11b+ Gr1+ myeloid cells (neutrophils) increased tumor growth and vascularization by producing MMP9 in Balb/c mice bearing MC colorectal cancer cells." (PMID 40050933, 2025). "At the FDR cut‐off at 0.05 and Log2FC cut‐off at 0.5, only one DEG was found (MMP9) in a G3 tumor, which was upregulated in tumor AOIs from ROIs with rich α‐SMA+ stromal cell presence." (PMID 39245631, 2025). "For example, DHA’s ability to reverse EMT markers (e.g., upregulation of E-Cadherin and downregulation of N-Cadherin, MMP-2, and MMP-9) suggests its potential to prevent tumor spread, a major challenge in NSCLC treatment." (PMID 40697663, 2025). "Here, we developed an integrated microfluidic system for the sensitive, accurate, totally on-chip exosome isolation and automatic quantification of tumor progression markers PD-L1 and MMP9." (PMID 41302727, 2025). "In this study, we analyzed the concentration of advanced oxidation protein products (AOPPs), expression of NF-κB, and the activity of MMP-9 in tumor tissue, adjacent tissue, and healthy control colon tissue." (PMID 40729026, 2025). "Abnormal expression of matrix metalloproteinases (MMPs), particularly MMP-2 and MMP-9, has been observed in tumors, and their involvement in tumor invasion and metastasis is widely recognized." (PMID 41220717, 2025).
tumor (continued). "For direct cytotoxicity, N1 TANs release ROS and matrix metalloproteinases 9 (MMP-9), which degrade the epithelial basement membrane, dismantling tumor support structures." (PMID 40805288, 2025). "Upregulation of Mmp3 and Mmp9 genes directly reflects tumor cells’ ability to breach physical barriers and acquire invasive capabilities." (PMID 41415031, 2025). "MMP9 is frequently overexpressed in CCA tissues and serum and is linked to aggressive tumor behavior and metastasis." (PMID 41300430, 2025). "Elevated MMP9 levels are strongly associated with HCC invasion and metastasis, and its inhibition has been shown to reduce tumor aggressiveness." (PMID 40630198, 2025). "MMP9 is involved in the development of the tumour microenvironment and is closely related to tumour metastasis." (PMID 40665344, 2025). "Matrix metalloproteinase‐9 (MMP9) showed mild‐to‐intense expression in the cancer cells and stromal cells in the tumor microenvironment." (PMID 40899568, 2025). "Several studies show that MMP-9 levels in serum or plasma can predict tumor metastatic potential and disease recurrence." (PMID 41573658, 2025). "In conclusion, by suppressing MMP-9 expression, CV limits tumor cell invasion and migration, especially in triple-negative breast cancer models." (PMID 41150756, 2025). "These cells contribute to the formation of an immunosuppressive tumor microenvironment and promote tumor progression by producing MMP9 and ARG1." (PMID 40740234, 2025). "Surgical parameters, VEGF levels, tumor markers [matrix metalloproteinase 9 (MMP9), stromal cell-derived factor-1a (SDF-1a), and carcinoembryonic antigen (CEA)], survival rates, and incidence of complications were compared between the two groups." (PMID 40821654, 2025). "The expression levels of Ki67, MMP2, and MMP9 in tumor tissues were determined via immunohistochemical (IHC)." (PMID 39944827, 2025). "Upon tumor-specific MMP2/MMP9-mediated digestion, loaded Pep-4 neo-peptide was released, and competitively bound to HLA molecule on tumor cells." (PMID 39748060, 2025). "Consistently, BBIT20 depleted EMT markers, particularly increasing E-cadherin and decreasing MMP-9 in tumour tissues, and markedly reduced the metastatic burden in the liver, a primary site of PDAC metastasis." (PMID 40275348, 2025). "Induction of apoptosis and prevention of metastasis of tumour cells by downregulating MMP-9 production and stopping the cell cycle at the Sub G1 phase." (PMID 40427522, 2025). "Neutrophil survival facilitated by GM-CSF leads to the secretion of various pro-inflammatory and angiogenic factors, such as IL-8, VEGF-A, TNF-α, and MMP-9, all contributing to tumor progression and angiogenesis." (PMID 40150133, 2025). "For instance, MMP-9 derived from osteoclasts has been shown toinfluence tumor growth within the bone microenvironment by promoting angiogenesis, without affectingthe osteolytic or osteogenic changes induced by the tumor." (PMID 40556678, 2025). "The mechanism of metastasis in various tumors, including HNSCC, is induced by the cooperation of extracellular HSP90 with MMP-2 and MMP-9, which disrupts the extracellular matrix and leads to the dissemination of tumor cells and formation of metastasis." (PMID 41369386, 2025). "Following early infiltration of tumor cells to the brain, activated astrocytes produce factors such as MMP-9, which promotes angiogenesis and release of growth factors from the extracellular matrix." (PMID 40076927, 2025). "Among these, MMP-14 emerged as being particularly relevant, given its association with disease status and risk of tumor recurrence, as well as its well-documented ability to activate other MMPs, including MMP-2 and MMP-9." (PMID 40869275, 2025). "Further investigation revealed that prostaglandin E2, a key substrate for ACOX1-mediated peroxisomal β-oxidation, enhances tumor cell invasiveness by activating the extracellular signal-regulated kinase (ERK)-matrix metallopeptidase 9 (MMP9) signaling pathway." (PMID 40821122, 2025).
tumor (continued). "We used in vivo fluorescence imaging to show that active MMP9 laterally increased with tumour growth in controls." (PMID 40442778, 2025). "To further explore the differences in metastasis and invasion among the three models, we examined the expression levels of MMP2 and MMP9, molecules involved in tumor metastasis." (PMID 41308696, 2025). "MMP9-expressing TAMs also play a significant role in creating an environment conducive to cancer metastasis, further promoting aggressive tumor characteristics and poor patient outcomes." (PMID 40858590, 2025). "Transforming growth factor-β1 (TGF-β1) enhances tumor cell migration and invasion by upregulating urokinase-type plasminogen activator (uPA) and matrix metalloproteinase-9 (MMP-9) via ROS-dependent signaling." (PMID 40549063, 2025). "Tumor heterogeneity, characterized by diverse cell populations with varying phenotypes and functional traits, contributes to heterogeneous MMP-9 expression." (PMID 40284474, 2025). "MMP2 and MMP9 mediate important steps in tumor angiogenesis by degrading ECM and basement membrane (BM), creating a conducive environment for the generation and extension of new blood vessels." (PMID 39781344, 2025). "MMP-9, a matrix metalloproteinase that degrades extracellular matrix components, was also reduced, potentially limiting tumor cell dissemination." (PMID 41472305, 2025). "MMP-9 cleavage induces fluorescence, enabling the visualization of abnormal pH and MMP-9 overexpression in tumor environments, facilitating tumor invasiveness assessment." (PMID 40284474, 2025). "Ellagic acid downregulates vascular endothelial growth factor (VEGF) and matrix metalloproteinases (MMP-2, MMP-9), thereby impairing tumor vascularization and metastatic potential." (PMID 41226270, 2025). "Another study revealed that TMZ treatment in GBM cells induces the upregulation of MMP-9, potentially promoting tumor invasion and a poor prognosis." (PMID 40265458, 2025). "Leptin, a key adipokine from CAAs, increases tumor cell invasion by upregulating invasion-related proteins like MMP-9 and S100A7." (PMID 40784879, 2025). "Specifically, we discuss the contribution of MMP-9 to tumor epithelial–mesenchymal transition, angiogenesis, and metastasis, as well as its involvement in a spectrum of vascular diseases, including macrovascular, cerebrovascular, and ocular vascular diseases." (PMID 40284474, 2025). "The article “Tissue-infiltrating neutrophils constitute the major in vivo source of angiogenesis-inducing MMP-9 in the tumor microenvironment” has the highest centrality." (PMID 40160822, 2025). "CEACAM5, upregulated under hypoxic conditions via HIF1α, activates the MAPK/ERK pathway in TAMs, leading to M2 polarization and increased extracellular matrix degradation through MMP9, which facilitates tumor cell migration and invasion." (PMID 40303340, 2025). "Neutrophils also play a significant role in promoting tumor cell detachment and metastasis through the secretion of MMP-9 and BV8." (PMID 40050933, 2025). "This, in turn, triggers VEGFA and MMP9 expression, facilitating tumor-induced lymphangiogenesis and LN metastasis." (PMID 40739091, 2025). "Consistent with our previous observations, we again detected enhanced MMP9 hotspots in the periphery of MUC-1 tumor spheroids." (PMID 41310103, 2025). "As regulator of the tumour microenvironment, MMP9 has key roles in cancer initiation, development, and progression via multiple mechanisms." (PMID 41240165, 2025). "Comprehensive imaging assessments were conducted to correlate tumor and edema volumes with MMP-9 levels." (PMID 41573658, 2025). "Tumour migration, invasion, and proliferation were significantly associated with E‐cadherin, vimentin, β‐catenin, MMP‐2, and MMP‐9." (PMID 40468625, 2025). "EMT cascade is a critical step in tumor metastasis which frequently accompanied with loss of E-cadherin expression and increased N-cadherin, VEGF, and MMP-9 expressions which prompt carcinoma metastasis and colonization." (PMID 41472816, 2025).